CCNA2 (cyclin A2)
Diseases named in the same sentence as CCNA2 in open-access papers (continued):
Sharing a sentence is not in itself a finding about the gene and the disease.
thyroid cancer (8 papers, 2002 to 2024). "FRA1 is recruited to the Cyclin A2 gene promoter and increases JUNB expression, which in turn binds to the Cyclin A2 gene promoter and promotes its expression, which has been reported in breast and thyroid cancers." (PMID 39085703, 2024). "In conclusion, our data demonstrate that SOSTDC1 is down-regulated in thyroid tumor tissues and inhibits thyroid cancer cell proliferation through modulating cyclin A2 and cyclin E2." (PMID 26378658, 2015). "The results showed that over-expression of SOSTDC1 in thyroid cancer cells resulted in dys-regulating the expression of critical cell cycle regulators, cyclin A2 and cyclin E2 in vitro and vivo." (PMID 26378658, 2015). "Therefore, SOSTDC1 inhibits the growth of thyroid cancer cells in vivo, likely by decreasing cyclin A2 and cyclin E2." (PMID 26378658, 2015). "Moreover, ectopic over-expression of SOSTDC1 led to down-regulation of cyclin A2 and cyclin E2, which subsequently inhibit thyroid cancer cell proliferation in vitro and in vivo." (PMID 26378658, 2015). "Moreover, our data suggest that SOSTDC1 inhibits the proliferation of thyroid cancer cells via regulation of cyclin A2 and cyclin E2." (PMID 26378658, 2015). "For instance, Cyclin A2 and Cyclin E2 can be mediated by SOSTDC1 and potentiate cell proliferation in thyroid cancer." (PMID 32154226, 2020). "Similar with the previous studies, our data demonstrated that decreased cyclin A2 and cyclin E2 were involved in the anti-proliferative role of SOSTDC1 in thyroid cancer." (PMID 26378658, 2015).
neuroblastoma (7 papers, 2013 to 2025). Neuroblastoma (NB) is the most common solid, extracranial childhood tumor. "We specifically studied MYCN, MYBL2, BIRC5, BARD1 and AURKA, poor prognosis markers of neuroblastoma, and CCNA2 and CCNE1 genes, involved in general carcinogenesis." (PMID 28467792, 2017).
viral infection (7 papers, 2010 to 2022). "We then set out to investigate the functional consequences of pUL21a-Cyclin A2 interaction in the context of viral infection." (PMID 25393019, 2014).
esophageal squamous cell carcinoma (6 papers, 2019 to 2022). Esophageal squamous cell carcinoma (ESCC) is a type of esophageal carcinoma (EC) that can affect any part of the esophagus, but is usually located in the upper or middle third. "For instance, CDCA7 regulate the expression of CCNA2 to facilitate the tumor progression of Esophageal Squamous Cell Carcinoma." (PMID 36313774, 2022).
lung squamous cell carcinoma (6 papers, 1998 to 2024). "The mRNA expression of BIRC5, SHCBP1, CCNA2, SKA3, and GINS1 in LUAD and lung squamous cell carcinoma (LUSC) tissues were all significantly higher than that in normal tissues." (PMID 34806315, 2022). "Five of the ten target drug genes are detected in lung squamous cell carcinoma tissues, whereas the expression of CCNA2, APOM, C4A, PKD2L1, and CYP21A2 was not very significant." (PMID 39175755, 2024).
psoriasis (6 papers, 2013 to 2024). An autoimmune condition characterized by red, well-delineated plaques with silvery scales that are usually on the extensor surfaces and scalp. "Since excess actin cytoskeleton organization is found in psoriatic skin lesions, cyclin A2 might also be involved in the abnormal actin cytoskeletal organization in the keratinocytes during psoriasis." (PMID 34639115, 2021). "We found that core genes (TOP2A, MELK) were highly expressed in psoriasis samples and lowly expressed in normal tissue samples, while DEPDC1B, CCNA2, DLGAP5, NUF2, ASPM were lowly expressed in psoriasis samples." (PMID 38382096, 2024). "The gene expression heatmap showed high expression of core genes (TOP2A, MELK) in psoriasis samples, while DEPDC1B, CCNA2, DLGAP5, NUF2, ASPM were lowly expressed in psoriasis samples." (PMID 38382096, 2024). "Many DEG-coded proteins (CCNA2, FYN, PIK3R1, CTGF, F3) and transcription factors (AR, TFDP1, MEF2A, MECOM) were identified as central nodes, suggesting their potential role in psoriasis pathogenesis." (PMID 24303025, 2013). "CCNA2, TFDP1 and MECOM might play role in the hyperproliferation of keratinocytes, whereas FYN may be involved in the disturbed immunity in psoriasis." (PMID 24303025, 2013).
Cirrhosis (5 papers, 2018 to 2025). A chronic disorder of the liver in which liver tissue becomes scarred and is partially replaced by regenerative nodules and fibrotic tissue resulting in loss of liver function. "It is concluded that BUB1B, NUSAP1, TTK, HMMR, CCNA2, and KIF2C can be considered as potential novel molecular indicators for the onset and development of HCC, since they are linked to the transition from cirrhosis to HCC." (PMID 36199789, 2022). "Finally, we believe that viral insertions and structural rearrangements activating CCNA2 or CCNE1 are early events triggering hepatocarcinogenesis because they occur in patients without cirrhosis and in absence of other oncogenic event like CTNNB1 mutations." (PMID 30531861, 2018).
endometriosis (5 papers, 2020 to 2025). The growth of functional endometrial tissue in anatomic sites outside the uterine body. "Then, we identified 11 potential mitosis-related downregulated hub genes, among which eight genes (KIF4A, BUB1B, NEK2, FBXO5, KIF11, CENPE, CCNA2, and NCAPG) showed good diagnostic properties of endometriosis and two genes (CCNA2, CENPE) were closely related to infertile endometriosis." (PMID 40772274, 2025). "Our study has identified eight potential mitosis hub genes (KIF4A, BUB1B, NEK2, FBXO5, KIF11, CENPE, CCNA2, and NCAPG) that exhibit excellent diagnostic properties for endometriosis." (PMID 40772274, 2025). "The PPI network analysis reveals hub genes, including BCL2, CCNA2, CDK7, EGF, GAS6, MAP3K7, and TAB2, which emerge as pivotal players in endometriosis progression." (PMID 39108650, 2024). "We finally found that CCNA2 and CENPE were related to infertile endometriosis." (PMID 40772274, 2025). "We used the GSE25628 dataset to detect the expression of selected target genes, and the results showed that the differential expression of eight MRHGs (KIF4A, BUB1B, NEK2, FBXO5, KIF11, CENPE, CCNA2, and NCAPG) between control and endometriosis patients was consistent with predictions." (PMID 40772274, 2025).
HCMV infection (5 papers, 2010 to 2020). "Whereas Cyclin D1 expression was largely unaffected by HCMV infection and all four viruses led to a strong and sustained induction of Cyclin E1, they markedly differed with respect to Cyclin A2, Cyclin B1 and APC5 protein regulation." (PMID 25393019, 2014). "However, we observed a high proportion of CDK1 in the nuclear fraction of UL21a-RXL2mut-infected cells, suggesting that Cyclin A2 down-regulation by pUL21a is also responsible for the limited nuclear availability of this essential mitotic kinase during HCMV infection." (PMID 25393019, 2014). "Therefore, to gain further insights into HCMV-induced SAMHD1 phosphorylation, we next asked whether Cdk1/2 were involved in T592 phosphorylation in response to HCMV infection, since cellular cyclin A2/Cdk1/2 complexes have been shown to phosphorylate SAMHD1 at T592." (PMID 32986788, 2020).
Infertility (5 papers, 2021 to 2025). "Given its ability to modulate steroid responsiveness in other cell types, we hypothesized that reduced expression of uterine CCNA2 may be associated with aberrant endometrial steroid signaling, leading to endometrial dysfunction and infertility." (PMID 39264721, 2024). "Notably, loss of Ccna2 in mouse models resulted in infertility." (PMID 39545416, 2024). "To fill this gap in our knowledge, we examined human endometrial tissue from fertile and infertile cisgender women for CCNA2 expression and correlated this with pregnancy outcome." (PMID 39264721, 2024). "In a PGRCre mouse model, uterine-specific ablation of Ccna2 resulted in infertility." (PMID 39545416, 2024). "Infertility is recapitulated in a conditional uterine knockout mouse model of Ccna2." (PMID 39264721, 2024). "Thus, CCNA2 may play an important role in fertility and may be part of the explanation for unexplained infertility; however, larger sample sizes will be required to further support this possibility." (PMID 39264721, 2024). "A study investigating CCNB1 and CCNA2 gene inhibition in mice found that both CCNB1-null and CCNA2-null mice exhibited infertility." (PMID 41153330, 2025). "Bax and Cyclin A2 levels in MenSCs from healthy volunteers remain constant, HDAC1 levels increase, and in MenSCs from patients with infertility change: Bax levels decrease and Cyclin A2 levels increase." (PMID 34202508, 2021).
multiple myeloma (5 papers, 2015 to 2020). "In this study, treatment of myeloma cells with DCZ0801 down-regulates the level of CDK2, Cyclin A2, and CDC 25A, which arrests the cell cycle in the S phase." (PMID 32626538, 2020).
myocardial infarction (5 papers, 2018 to 2024). Gross necrosis of the myocardium, as a result of interruption of the blood supply to the area, as in coronary thrombosis. "Previous studies have shown that the overexpression of cyclin D2 and cyclin A2 in the hearts of rats with myocardial infarction can induce cardiomyocyte proliferation and facilitate the repair of scarred areas following myocardial infarction." (PMID 39080192, 2024). "Similar results were also seen in cyclin A2-overexpressing transgenic mice, including the induction of cardiac regeneration, reduced scarring, improved LV function, and prevention of heart failure after myocardial infarction." (PMID 33013405, 2020). "CCNA2 is a crucial regulator of cell proliferation, its sustained expression in the heart invokes cardiomyocyte mitosis to promote cardiomyocyte proliferation and regeneration, thereby improving cardiac function in rodents with myocardial infarction and heart failure." (PMID 39243097, 2024). "Overexpression of cell cycle-related gene regulators, such as Cyclin A2, Cyclin D1, and Cyclin D2, could enhance CM cell cycle activity and improve repair following myocardial infarction (MI) 4-6." (PMID 34646377, 2021).
nasopharyngeal carcinoma (5 papers, 2016 to 2025). A carcinoma arising from the nasopharyngeal epithelium. "CCNA2 protein was significantly decreased in tumor tissues harvested from miR-188-injected mice; miR-188 suppressed nasopharyngeal carcinoma initiation and progression in vivo potentially via the downregulation of genes involved in G1/S transition." (PMID 40345591, 2025). "Overexpression of miR-188 inhibits cell proliferation, tumor colony formation and G1/S cell cycle transition in human nasopharyngeal carcinoma CNE cells by inhibiting CCND1, CCND3, CCNE1, CCNA2, CDK4 and CDK243." (PMID 27708404, 2016).
Obesity (5 papers, 2010 to 2024). Accumulation of substantial excess body fat. "The WAT of db/db mice also exhibited similar changes in Ccna2 mRNA compared to that of control m/m mice during the development of obesity." (PMID 29866655, 2018). "Other module genes related to lipid metabolism and obesity include Anxa5 (annexin A5), Ccna2 (cyclin A2), Ces5 (carboxylesterase 5), Cyp2c38 (cytochrome P450, family 2, subfamily c, polypeptide 38), Setd8 (SET domain containing 8), and Slc16a11 (monocarboxylic acid transporters, member 11)." (PMID 21179437, 2010). "In addition, in vivo data suggest an involvement of cyclin A2 in development of obesity." (PMID 29866655, 2018). "Moreover, m6A-YTHDF2-FTO signaling way might be crucial for the development of obesity, m6A—binding protein YTHDF2 can methylate mRNAs of cyclin A2 (CCNA2) and cyclin dependent kinase 2 (CDK2), and then reduce their protein expression to prolong cell cycle progression and suppress adipogenesis." (PMID 32110378, 2020).
pancreatic ductal adenocarcinoma (5 papers, 2019 to 2023). An infiltrating adenocarcinoma that arises from the epithelial cells of the pancreas. "Overexpression of CCNA2 is associated with poorer OS and DFS in pancreatic ductal adenocarcinoma, and CCNA2 overexpression is associated with disease progression in pancreatic ductal adenocarcinoma." (PMID 36874006, 2023).
colorectal adenocarcinoma (4 papers, 2016 to 2021). The most common type of colorectal carcinoma. "We found that among the 12 central genes, CCNA2, MAD2L1, DLGAP5, and AURKA were associated with the overall survival of colorectal adenocarcinoma (P < 0.05), and RRM2 and AURKA were associated with disease-free survival of colorectal adenocarcinoma (P < 0.05)." (PMID 33519906, 2020).
lymph node metastasis (4 papers, 2004 to 2022). "Our study showed that the abnormal expression of CCNA2 was also significantly related to the overall survival time, pathological stage of the tumor, and lymph node metastasis." (PMID 33519906, 2020). "In terms of lymph node metastasis, the expression of CCNA2 was significantly increased in N1 and N2, but not in N3." (PMID 33519906, 2020).
squamous carcinoma (4 papers, 2006 to 2018).
acute myeloid leukemia (3 papers, 2022 to 2025). Acute myeloid leukemia (AML) is a group of neoplasms arising from precursor cells committed to the myeloid cell-line differentiation. "The upregulation of BUB1B, CCNA2, and CCNB2 in pathway studies is associated with the development of Human T-cell leukemia virus 1 infection and Acute myeloid leukemia." (PMID 40100920, 2025).
bladder urothelial carcinoma (3 papers, 2020 to 2022). "CCNA2 plays important role in S/G2 transformation and G2 phase checkpoint in human urinary bladder transitional cell carcinoma treated with fluid shear stress." (PMID 33941187, 2021).
cholangiocarcinoma (3 papers, 2020 to 2021). A carcinoma that arises from the intrahepatic biliary tree (intrahepatic cholangiocarcinoma) or from the junction, or adjacent to the junction, of the right and left hepatic ducts (hilar cholangiocarcinoma). "However, CD36, GGCX, UBASH3B, DBN1, PTTG1, CCNA2, and SPATS2 are found in other tumors to regulate tumor progression, which may also regulate cholangiocarcinoma progression and affect the recurrence of CCA." (PMID 32071556, 2020).
colon adenocarcinoma (3 papers, 2021 to 2025). "CCNA2 expression was lower in metastases relative to that in matched primary colon adenocarcinoma, suggesting that CCNA2 negatively controlled motility by promoting RhoA activation, thereby showing a new function of CCNA2 in cytoskeletal rearrangement and cell migration." (PMID 40345591, 2025). "In colon adenocarcinoma, the somatic copy number alterations (SCNAs) of CCNA2 correlated with the infiltration levels of B cells, CD8+ T cells, and dendritic cells; in rectum adenocarcinoma, somatic copy number alteration (SCNA) of CCNA2 correlated with the infiltration levels of macrophages." (PMID 40345591, 2025).
COVID-19 (3 papers, 2022 to 2023). A disease caused by infection with severe acute respiratory syndrome coronavirus 2. "Therefore, Cyclin A2 may be another potential target for the treatment of COVID-19 and IS through the mechanism of affecting the level of cyclin B1/CDK1." (PMID 37184686, 2023). "We screened for statistically significant hub genes and found that ACTB was in low expression of both BD and COVID-19, and ASPM, CCNA2, CCNB1, and CENPE were in low expression of BD and high expression of COVID-19." (PMID 37335738, 2023).
germ cell tumor (3 papers, 2008 to 2022). A benign or malignant, gonadal or extragonadal neoplasm that originates from germ cells. "Elevated expression of cyclin A2 and their catalytic partners CDK1 and CDK2 have been detected in male germ cell tumors, and their levels are quantitatively associated with tumor invasiveness." (PMID 25782154, 2015).
heart failure (3 papers, 2020 to 2024). Inability of the heart to pump blood at an adequate rate to meet tissue metabolic requirements. "Other studies have delivered cyclin A2 to the heart by injection of an adenoviral vector in a heart failure rat model or by injection of cyclin A2-encoding adenovirus into an MI pig model." (PMID 34360531, 2021).
hepatoblastoma (3 papers, 2022 to 2026). Hepatoblastoma (HB) is a malignant hepatic tumor and is the most common pediatric liver cancer. "In hepatoblastoma, CCNA2, CDK1, and CDC20 were identified as potential therapeutic targets, with their knockdown inhibiting aggressive cell behaviors." (PMID 41511815, 2026). "CDK1 and CCNA2 have excellent performance in AUC value, sensitivity and specificity and have been identified as biomarkers in hepatoblastoma, so their functions and roles have been relatively clear." (PMID 40231267, 2025). "Increased co-expression of CCNA2 and CDK1 has been observed in hepatoblastoma, and inhibiting the expression of CCNA2 and CDK1 attenuates the proliferative, migrative, and invasive capacities of both HepG2 and HuH-6 cells." (PMID 35681641, 2022).
metastatic disease (3 papers, 1999 to 2010). "It is clear that nearest neighbors of MYBL2 (e.g CCNA2) also undergo increases in entropy, thus implicating larger gene modules, in this case a cell-cycle module, that are altered in metastatic disease." (PMID 20673354, 2010).
myeloid leukemia (3 papers, 2009 to 2023). A clonal proliferation of myeloid cells and their precursors in the bone marrow, peripheral blood, and spleen. "CCNA2 has been reported to be a key regulator of cell differentiation, and it can switch the differentiation pathways of human myeloid leukemia K562 cells." (PMID 27020049, 2016). "Our results demonstrate the pro-apoptotic role of cyclin A2 in human myeloid leukemia K562 cells, and indicate that cells with low level of cyclin A2 were more resistant to chemotherapeutic agent DOX." (PMID 19684852, 2009).
oral squamous cell carcinoma (3 papers, 2025 to 2026). "We found that the inhibition of the CBP/β-catenin axis mediated by ICG-001 in oral squamous cell carcinoma led to the downregulation of BIRC5, EZH2, AURKA, CCNA2, and other genes previously implicated in therapy resistance." (PMID 41227355, 2025).
ovarian tumor (3 papers, 2004 to 2024). "siRNA-mediated CCNA2 knockdown confirmed this observation by right shifting the IC50 of response to prexasertib in NCI-H520 cells as well as in the ovarian tumor line OVCAR3." (PMID 32076484, 2020).
pancreatic adenocarcinoma (3 papers, 2018 to 2024). "CCNA2 has been demonstrated up-regulated in pancreatic adenocarcinoma tissue samples and significantly involved in the cell cycle pathway." (PMID 29596435, 2018).
pituitary adenomas (3 papers, 2021 to 2023). "Another miRNA that regulates expression of CCNA2, namely miR‐130b has been shown to be dysregulated in pituitary adenomas." (PMID 37933082, 2023). "Moreover, the expression level of HMGA2 and cyclin A2 (CCNA2) that these miRNAs target was upregulated in human pituitary adenomas." (PMID 36010855, 2022).
pituitary tumor (3 papers, 2018 to 2024). A benign or malignant neoplasm affecting the pituitary gland. "In GH3 rat pituitary tumor cells, miR-130b inhibited cell proliferation by arresting the cells in the G1 and G2 phase of the cell cycle through targeting cyclin A2 gene." (PMID 29849932, 2018).
rectal cancer (3 papers, 2006 to 2012). A primary or metastatic malignant neoplasm that affects the rectum. "Thus, in rectal cancer, we believe overexpression of cyclin A2 protein is caused mainly by impaired degradation of the protein." (PMID 20029639, 2009). "A statistically significant correlation was also observed between overexpression of cyclin A2 and local relapse of rectal carcinomas." (PMID 20029639, 2009).
clear cell renal cell carcinoma (2 papers, 2022 to 2023). "CCNA2 may significantly influence the prognosis of multiple cancer types, especially clear cell renal cell carcinoma (ccRCC)." (PMID 35401923, 2022).
dementia (2 papers, 2016). Loss of intellectual abilities interfering with an individual's social and occupational functions. "In general, cyclins (CCNA2) were shown to increase the severity of Alzheimer-related pathology and other types of dementia." (PMID 26784894, 2016).